XPC (XPC complex subunit, DNA damage recognition and repair factor)
Diseases named in the same sentence as XPC in open-access papers (continued):
Sharing a sentence is not in itself a finding about the gene and the disease.
cancer (continued). "Statistical analysis on immunohistochemistry data suggested that XPC (+) expression was significantly higher in well differentiated cancer tissue than poor differentiated cancer tissue (P < 0.05)." (PMID 30109214, 2018). "XPC (+) expression was 73.2% in well differentiated cancer tissue, 62.3 and 46.6% in moderately differentiated and poor differentiated cancer tissue, respectively." (PMID 30109214, 2018). "Exploiting the high proliferative rate of cancer cells and the slow dissociation rate of XPC from clustered adducts allows for a more efficiently targeted approach to cancer therapy." (PMID 27327897, 2016). "As a DNA repair factor, XPC helps to maintain a low level of endogenous DNA lesions in the cancer cells." (PMID 25871391, 2015). "It has also been found that apoptosis induced by DNA damage as a consequence of XPC polymorphism makes people more prone to develop MCTR, as well as cancers." (PMID 26604426, 2015). "The results of statistical analysis on immunohistochemistry data suggested that the proportions of XPF (−) and XPC (−) were significantly higher in high grade papillary cancer tissues than in PUNLMP cancer tissues (P<0.05)." (PMID 25535740, 2014). "There is a strong correlation between reduced XPC mRNA and protein levels and increased resistance of cancer cells to cisplatin treatment." (PMID 23940574, 2013). "We did not identify any cancer-predisposing germline variants except in the XPC gene in the studied patients." (PMID 37567969, 2023). "In patients with NSCLC, low tumor XPC mRNA expression is associated with advanced stage at diagnosis and an increased rate of cancer relapse after treatment in never-smokers." (PMID 35530314, 2022). "Since increased NER repair could mean increased resistance to platinum-based therapy, inhibiting XPC could be a viable option to overcome platinum resistance in cancer cells." (PMID 35530314, 2022). "Additionally, research supports a role of XPC in the prognosis and treatment response in several of these cancers." (PMID 35530314, 2022). "Tight control of XPC ubiquitination is likely required to ensure DNA repair and may be dysregulated in human cancers." (PMID 35530314, 2022). "Although it is still poorly understood, the characterization of the proteomic signature of an XPC mutant is essential to identify mediators that could be targeted to prevent cancer development in XPC patients." (PMID 34630850, 2021). "Additionally, studies involving many different cancer cell lines have shown that the overexpression of XPC leads to cisplatin resistance while knockout of the gene enhances sensitivity." (PMID 34360968, 2021). "Studies have shown that enhanced expression of XPC increases resistance in many types of cancer." (PMID 34360968, 2021). "Additionally, two heterozygous variants in autosomal recessive genes associated with cancer predisposition, were identified in MUTYH gene and XPC gene (each in 1 patient)." (PMID 31937788, 2020). "XPC rs2228001 is one of the most extensively studied NER pathway SNPs, as numerous case-control association studies and meta-analyses have been performed to investigate its potential role on cancer predisposition." (PMID 31374908, 2019). "XPC protein expression was also measured in normal andcolorectal cancer tissues." (PMID 30109214, 2018). "Polymorphisms in the XPC gene may alter the NER capacity and affect genetic predisposition to cancer." (PMID 27246180, 2016). "In addition, the PPP1R13L, CD3EAP and ERCC1 polymorphisms are in linkage disequilibrium with each other in cancers, and XPC rs2228001 and rs2279017 and XPF rs4781560, which are located in the same region, had significant linkage disequilibrium." (PMID 26681190, 2015). "Furthermore, the proportions of XPF and XPC with concurrently reduced expression were significantly higher in high grade papillary cancer tissues than in PUNLMP cancer tissues (P<0.05)." (PMID 25535740, 2014).
cancer (continued). "Defective XPC functioning has been shown to result in a cancer prone phenotype." (PMID 23118991, 2012). "In individuals with impaired XPC function due to genetic variations, the accumulation of DNA damage may be accelerated, leading to increased genomic instability, a well‐known driver of cancer recurrence and progression after surgical intervention." (PMID 40833230, 2025). "However, cancer cells are characterized by inhibition of apoptosis, raising the question of whether XPC differentially impacts cellular response to CS in benign epithelial and cancer cells." (PMID 40060594, 2025). "These XPC-deficient, MSH6-low cells effectively repaired UV- and cisplatin-induced lesions by TC-NER, suggesting that the previously observed MMR-NER interactions may rest in interactions with proteins involved in GG-NER, particularly in cancer development." (PMID 35530314, 2022). "However, most of the reported XPC mutations also give rise to stop codons and did not appear to be associated with a high level of internal cancers." (PMID 35246173, 2022). "As the ERCC5 (XPG) correlations could point to multiple associations, we tested other NER proteins, e.g., XPA and XPC, and found that they generally did not exhibit the same characteristics in these three cancer types, except for XPA in MESO." (PMID 34966786, 2021). "In terms of regulation of cellular respiration, the reduced protein level of XPC in human cancer cells may result in a metabolic shift from mitochondrial oxidative phosphorylation (OXPHOS) to anaerobic glycolysis in response to the accumulation of nuclear DNA damage and increased oxidant production." (PMID 31551763, 2019). "Therefore, we still cannot rule out the possible genetic role played by XPC rs2228000 in the risk of cancers of the blood or nervous systems." (PMID 31710080, 2019). "However, the effects of XPC SNPs on cancer risk have not been fully validated, and further functional studies should be performed to unravel the underlying mechanisms." (PMID 27974699, 2017). "Although modified base recognition and augmentation of BER glycosylase and APE1 endonuclease activity have all been proposed, exactly how XPC is involved in BER of oxidized DNA lesions and the subsequent cancer development remain areas of active research." (PMID 35530314, 2022). "Immunohistochemistry (IHC) was used to detect the expression of XPC and CD133 in cancer and paracancerous tissues." (PMID 34803670, 2021). "While the observations in cancer cell lines show a clear correlation between cisplatin sensitivity and XPC protein levels, whether or not resistance in cisplatin-treated tumors is associated with upregulated XPC has not been analyzed." (PMID 33291532, 2020). "XPC protein is an important DNA damage recognition protein and an initiator of the NER process that defends against cancer." (PMID 27847809, 2016). "Thirty proteins, excluding RORA, XPC and ERCC2, are known to play important roles in the expression of malignant phenotypes involved in cancer initiation and/or progression, such as increased invasion, aberrant metabolism and enhanced survival." (PMID 26703734, 2015). "It was found that the proportions of XPF (−) and XPC (−) were 54.4% and 50.0% in the high grade papillary cancer tissue, 39.7% and 37.9% in PUNLMP cancer tissues and 49.5% and 45.2% in low grade papillary cancer tissues." (PMID 25535740, 2014). "Similarly, interactions between XPC/XRCC3 and XPD/XRCC3 were observed, suggesting that coordination between both repair systems might contribute to the individual susceptibility to develop cancer." (PMID 17705814, 2007). "No particular type of cancer shows higher co-occurrence with STK19 mutation, and the XPC, XPE, and STK19 genes have similar somatic mutation frequencies." (PMID 38890355, 2024).
cancer (continued). "The UV‐DDB complex, including DDB1 (LoH: 10.4%) and DDB2 (LoH: 8.0%), facilitates binding of XPC to UVR‐induced lesions, and experimental evidence suggests its knockdown increases tumorigenic potential and reduces overall survival in various cancers." (PMID 35229492, 2022). "Future studies would benefit from studying XPC as a biomarker of cancer prognosis and response to treatment in non-dermatologic malignancies." (PMID 35530314, 2022). "From these group of genes, XPC, GSTP1, and ITGA5 were validated on breats cancer samples from TCGA." (PMID 32078659, 2020). "Here, we describe a new model for XPC activation of NER where the off-rate of XPC from the lesion site, particularly in the case of clustered lesions, is the rate-limiting step of NER, and propose applying this finding to design a more efficiently targeted approach to cancer therapy." (PMID 27327897, 2016). "Regulation of the nucleotide excision repair genes XPC and ERCC2 contributes to cancer prevention rather than progression, because the function of these genes is to maintain genomic integrity." (PMID 26703734, 2015).
tumor (50 papers, 2005 to 2025). "Stratified analyses by age, gender, smoking status, pack-year, drinking status, tumor sites, and Duke’s stages demonstrated a significant association between the XPC rs2228001 variant allele and increased CRC risk in participants at 57 years of age or under, non-smokers, and non-drinkers." (PMID 27669310, 2016). "However, various modes of transcriptional regulation have been implicated in altered tumor XPC expression as well, and XPC expression may be altered in cells outside of the tumor itself." (PMID 35530314, 2022). "The XPC gene, along with several other tumor suppressor genes, is located on chromosome 3p, a frequently site of chromosomal deletion in human tumors." (PMID 35530314, 2022). "We found MIBC cells are hypermutable, deficient in DNA repair and have markedly downregulated DNA repair genes, XPC, hOGG1/2 and Ref1, and the tumor suppressor, TAp63γ." (PMID 34747697, 2021). "While mechanistic details remain, our data provide compelling evidence that USP44 stabilizes DDB2 and that this mechanism is crucial for efficient XPC recruitment and has physiological relevant roles in tumor prevention." (PMID 33937266, 2021). "DNA repair genes such as XPC, Ref1, and hOGG1/2, and TAp63γ, the tumor suppressor isoform of p63, are suppressed in MIBC cells but are highly expressed in NMIBC cells." (PMID 34747697, 2021). "Low expression of WDR48 and XPC was related to a large tumor diameter (p = 0.01 and p = 0.004, respectively), and a mixed/epithelioid cell type (p = 0.007 and p = 0.03, respectively)." (PMID 31382494, 2019). "Our results were similar to the results of previous studies that found that low XPC expression can promote tumor progression." (PMID 30109214, 2018). "XPC expression is also reduced in the tumor tissue of resistant patients compared to normal lung tissue." (PMID 28746345, 2017). "More interestingly, XPC correlated with age of diagnosis in our tumour cohort (rs = 0.213, p = 0.037) indicating older age of diagnosis had higher XPC transcript levels." (PMID 27487145, 2016). "In line with previous studies, we found that attenuated XPC protein expression is a common phenomenon in BC, both in dissociated tumor cells as well as in FFPE samples." (PMID 25927440, 2015). "Tumor xenografts initiated with A549-shXPC cells grew faster than those derived from XPC-proficient A549-shCtrl cells." (PMID 25871391, 2015). "XPC silencing is also able to decrease DNA damage-induced apoptosis and renders tumor cells therapy resistance." (PMID 25871391, 2015). "The expression levels of XPF and XPC were slightly lower in the tumor tissues of heavy smokers than in those of mildly smoking patients." (PMID 25535740, 2014). "Among the DNA mismatch repair gene MLH1 (3p21.3-p23) and the DNA repair gene XPC (3p25.23), which is frequently found mutated in Xeroderma pigmentosum syndrome type C, this locus contains the VHL (von Hippel-Lindau) tumor suppressor gene." (PMID 23127113, 2012).
tumor (continued). "On the other hand, this inhibition may help to sensitize tumor cells to other therapies due to the involvement of XPC in other DNA repair pathways and in checkpoint activation." (PMID 35530314, 2022). "With regard to associations between gene expression and tumor diameter, we noticed an association between low expression of WDR48 and XPC and a large LBD (p = 0.01 and p = 0.004, respectively), while a high expression of CENPX correlated with a large LBD (p = 0.02)." (PMID 31382494, 2019). "These analyses further confirmed the tumor suppressor role of XPC in NSCLC." (PMID 25871391, 2015). "Thus, attempts to improve the XPC photosensitive and deficient repair phenotype using PIK3C3 inhibitors could pave a way for new therapeutic approaches delaying or preventing tumor initiation." (PMID 39562566, 2024). "This analysis revealed that the XP-C tumor mutational profiles and their NMF-derived mutational Signature “C” had the highest similarity to the COSMIC Signature 8 (cosine similarity of 0.87−0.92, and 0.86 respectively) and formed a cluster together with XPC and Ercc1 organoid knockouts." (PMID 33203900, 2020). "It was clearly demonstrated that XPC mutations and deletions do not shorten lifespan in mice rather perhaps could be early events that induce late onset, slow growth/progression of tumor." (PMID 33329698, 2020). "The differential analysis filtered for processes driven by CD271 in tumor-initiating cells also revealed enrichment for the genes participating in nucleotide excision repair (NER, including damage recognition and repair factor XPC, DNA repair associated BRCA2, UBE2I, COPS7A, POLD3, USP45, RFC5)." (PMID 31118427, 2019). "Finally, to investigate whether tumor recurrence has any impact on XPC protein expression levels we collected additional clinically relevant data and compared XPC protein levels from primary NMIBC to that of recurrent NMIBC." (PMID 25927440, 2015). "LOH is a common mechanism of tumor suppressor inactivation, and the relevant region on chromosome 3 contains several tumor suppressor genes, including VHL, XPC, and MLH1." (PMID 41279090, 2025). "In addition, reduced levels of XPC protein may also be a contributing factor in tumor cell resistance to many commonly used DNA-damaging anticancer drugs because of the role of the XPC protein in initiating important cellular responses such as apoptosis following the treatment with these drugs." (PMID 21507255, 2011). "In summary, we demonstrated that circ_0004470 regulates BPDE-induced DNA damage by interacting with XPC and DDB1, thereby facilitating the acquisition of cellular oncological phenotypes, including malignant proliferation, metastasis, and tumor-forming capacity." (PMID 40157540, 2025). "BTG2, p73, and XPC were up-regulated, however the differences in these between 177Lu-trastuzumab and 177Lu-HuIgG treated tumor tissue was not significant." (PMID 27196891, 2016).
tumor (continued). "The other tumor showed XPC and UDS levels similar to that of XPC-/- cells." (PMID 25927440, 2015). "In this way we also noticed that one tumor with lower UDS showed higher levels of residual repair capacity than an XPC-/- cell, indicating that NER was not completely abrogated in that sample." (PMID 25927440, 2015). "Our findings provide further support for the notion that SNPs in DNA repair genes, particularly in the XPC and PARP1 genes, may serve as prognostic biomarkers for patients with CCA, and highlight the importance of the DNA repair pathways in modulating tumour biology after surgical resection." (PMID 40833230, 2025). "Use of this global XPC knock-down mouse model does not allow for differential evaluation of XPC impact on other cells of the tumor microenvironment (e.g., stromal-mesenchymal and local tumor immune cells) and their potential role in LUSC development and proliferation." (PMID 38672576, 2024). "In addition, we did not observe a correlation between XPC expression and tumor grade or stage, nor did we observe a relation with tumor recurrence risk." (PMID 25927440, 2015).
hematological malignancies (4 papers, 2022 to 2024). "Among these 31 patients, 2 are XP-V (6.5%) and 29 are XP-C (93.5%) among which 28 (90%) originated from North Africa, and carry the XPC delTG mutation: 59% are hematological malignancies, 17% gynecological tumors, 10% THY tumors and 10% CNS tumors." (PMID 35246173, 2022).
gynecological tumors (3 papers, 2022 to 2025). "In this work, we describe young patients with constitutive biallelic deactivation of the XPC gene developing gynecological tumors with somatic DICER1 mutations." (PMID 37567969, 2023).
neurological disease (3 papers, 2013 to 2021). "The data about XPC function in glycosylase—BER oxidative base lesion sensors—stimulation raise questions about the relevance of these interactions as far as they absence in XP-C CGs does not lead to neurological disease." (PMID 34207557, 2021). "Mutations in XPC and XPE subtypes, which usually do not lead to neurological disease, can present central nervous system abnormalities due genetic and environmental modifier factors." (PMID 23755135, 2014). "Only patients with XPC, XPE and XP variant do not have neurological disorders, while the others show major and progressive neurological abnormalities." (PMID 23497518, 2013).